CDK5RAP3 (CDK5 regulatory subunit associated protein 3)
Diseases named in the same sentence as CDK5RAP3 in open-access papers (continued):
Sharing a sentence is not in itself a finding about the gene and the disease.
colitis (5 papers, 2020 to 2023). Inflammation of the colon. "IEC-specific deletion of Cdk5rap3 led to nearly complete loss of Paneth cells and increased susceptibility to experimentally induced colitis." (PMID 33504792, 2021). "Additionally, intestinal epithelial cell (IEC)-specific Cdk5rap3 knockout mice displayed a nearly complete loss of Paneth cells and increased susceptibility to colitis, indicating the essential role of Cdk5rap3 in Paneth cell development and maintenance." (PMID 36843575, 2023). "Furthermore, intestinal epithelial cell-specific CDK5RAP3-KO mice showed an almost complete absence of Paneth cells and an increased susceptibility to experimentally-induced colitis, suggesting a key role for CDK5RAP3 in Paneth cell development and maintenance." (PMID 37947621, 2023). "The AS events of CDK5-regulatory subunit associated protein 3 (Cdk5rap3) and TRM5 tRNA methyltransferase 5 (Trmts) in acute colitis model were consistent with the rMATS results." (PMID 37158534, 2023). "Specifically, ablation of any of them (UFL1/DDRGK1/CDK5RAP3) in intestinal epithelial cell (IEC)-specific knockout mice displayed disappear of Paneth cells, leading to an imbalance of intestinal microbiota and increased susceptibility to colitis." (PMID 36843575, 2023). "IEC-specific knockout of Cdk5rap3 led to nearly complete absence of Paneth cells and increased susceptibility to experimentally induced colitis." (PMID 33504792, 2021).
renal carcinoma (4 papers, 2019 to 2025). A carcinoma arising from the epithelium of the renal parenchyma or the renal pelvis. "In renal cancer, CDK5RAP3 is downregulated in renal cancer tissues and participates in autophagy regulation in renal cancer cell lines." (PMID 34722315, 2021). "To explore the role of CDK5RAP3 in renal cancer, we recruited 25 renal cancer patients diagnosed as clear cell renal cell carcinoma from histologic results." (PMID 31061682, 2019). "More importantly, we found that CDK5RAP3 participated in the regulation of autophagy in renal cancer." (PMID 31061682, 2019). "In contrast, the staining intensity of CDK5RAP3 in renal cancer was weaker compared with the paracancerous tissues." (PMID 31061682, 2019). "In the present study, we observed that CDK5RAP3 was downregulated and regulated cell viability in renal cancer." (PMID 31061682, 2019). "In the present study, we identified that CDK5 regulatory subunit-associated protein 3 (CDK5RAP3), a putative tumor suppressor in many cancers, was downregulated in renal cancer tissues." (PMID 31061682, 2019). "Taken together, our data demonstrated that the expression of CDK5RAP3 was downregulated in renal cancer compared with the paracancerous tissues." (PMID 31061682, 2019). "Through loss- and gain-of-function experiments, we observed that the action of CDK5RAP3 in renal cancer cells was different in Caki-1 and 769-P cell lines." (PMID 31061682, 2019). "To explore the function of CDK5RAP3 in renal cancer, we initially detected the expressions of CDK5RAP3 in four commonly used renal cancer cell lines: 769-P, 786-O, Caki-1, and Caki-2 cells." (PMID 31061682, 2019). "We found that the expression intensity of CDK5RAP3 in renal cancer tissues was reduced to 56.1% of the paracancerous tissues." (PMID 31061682, 2019). "In the present study, we found that CDK5RAP3 was downregulated in renal cancer and participated in the regulation of apoptosis and cell viability." (PMID 31061682, 2019). "However, in gastric tumour tissues and renal cancer tissues, the CDK5RAP3 expression of mRNA and protein levels was lower as compared with surrounding non‐tumour tissues." (PMID 35509151, 2022). "The role of CDK5RAP3 in autophagy in renal cancer has been identified; however, the mechanism remains unclear." (PMID 35509151, 2022). "Among them, CDK5RAP3 is reported to regulate autophagy in a renal cancer model." (PMID 34722315, 2021). "However, CDK5RAP3 was significantly downregulated in renal cancer compared with paracancerous renal tissues." (PMID 31061682, 2019). "Overexpression of CDK5RAP3 in 769-P cells resulted in the activation of autophagy, which indicated that CDK5RAP3 might participate in the regulation of autophagy in renal cancer." (PMID 31061682, 2019). "CDK5RAP3 is a potential tumor suppressor and participates in autophagy regulation in renal cancer, which suggests CDK5RAP3 could be a candidate biomarker for individualized treatment." (PMID 31061682, 2019). "In the present study, we found that the expression of CDK5RAP3 was downregulated in renal cancer tissues and may participate in the regulation of cell viability and autophagy in renal cancer." (PMID 31061682, 2019). "In addition, we observed that CDK5RAP3 participated in the regulation of autophagy in renal cancer." (PMID 31061682, 2019). "Our findings indicate that CDK5RAP3 may be a novel biomarker of renal cancer." (PMID 31061682, 2019). "Similar to GC, CDK5RAP3 and UFL1 also play a tumor suppressing role in renal carcinoma and melanoma, respectively." (PMID 41179291, 2025). "Compared with adjacent non-tumor tissues, CDK5RAP3 expression is significantly downregulated in renal carcinoma." (PMID 41179291, 2025). "However, there have been no reports on the relationship between CDK5RAP3 and renal cancer until recently." (PMID 31061682, 2019).
colon adenocarcinoma (3 papers, 2018 to 2022). "CDK5RAP3 is overexpressed in human HCCs, lung adenocarcinoma and colon adenocarcinoma, and high levels of CDK5RAP3 activate PAK4 (p21‐activated protein kinase 4) to enhance HCC metastasis." (PMID 35509151, 2022). "For instance, IC53, a kind of CDK5RAP3 isoforms, is demonstrated to be positively correlated with the grade and invasion depth in colon adenocarcinoma, and enhance cell proliferation, migration, adhesion, and tumorigenicity of human colon cancer cell lines." (PMID 34722315, 2021).
lung adenocarcinoma (3 papers, 2016 to 2022). A carcinoma that arises from the lung and is characterized by the presence of malignant glandular epithelial cells. "Furthermore, UFL1, a binding partner of CDK5RAP3, is also identified as a putative tumor suppressor in hepatocarcinoma or a potential oncogene in lung adenocarcinoma." (PMID 34722315, 2021). "First, CDK5RAP3 is proved to be overexpressed in lung adenocarcinoma tissues." (PMID 34722315, 2021). "Overexpressed CDK5RAP3 and CCNB2, as well as suppressed RAGE, may be promising biomarkers in lung adenocarcinoma." (PMID 27610375, 2016).
lymph node metastasis (3 papers, 2018 to 2022). "Univariate analysis revealed that depth of invasion, lymph node metastasis, distant metastasis, and CDK5RAP3 and MCM6 expression were associated with patients' overall survival." (PMID 31528213, 2019). "Univariate analysis revealed that tumor size, histology, depth of invasion, lymph node metastasis, distant metastasis and CDK5RAP3 and p-AKT (Ser473) expression were associated with overall survival." (PMID 29540196, 2018).
osteosarcoma (3 papers, 2012 to 2018). A usually aggressive malignant bone-forming mesenchymal neoplasm, predominantly affecting adolescents and young adults. "In addition, low expression of CDK5RAP3 inhibits the invasion, migration and proliferation of U2OS osteosarcoma cells." (PMID 29540196, 2018).
anemia (2 papers, 2021). A reduction in the number of red blood cells, the amount of hemoglobin, and/or the volume of packed red blood cells. "Recent studies have revealed that CDK5RAP3 knockout mice display liver degeneration, regeneration, anemia, and hemorrhage, as well as metabolic disorders such as hypoglycemia and impaired lipid metabolism, indicating that CDK5RAP3 may be associated with hepatic, hematological and metabolic diseases." (PMID 34722315, 2021). "Additionally, no severe anemia was observed in adult Cdk5rap3 conditional KO mice (our unpublished observation), suggesting that unlike other components of the Ufm1 system, Cdk5rap3 is not essential for red blood cell development." (PMID 33504792, 2021).
cervical carcinoma (2 papers, 2020 to 2021). A carcinoma arising from either the exocervical squamous epithelium or the endocervical glandular epithelium. "Fourth, CDK5RAP3 is markedly overexpressed in cervical carcinoma based on the data from several online databases and enhances the proliferation and tumorigenicity in cervical carcinoma cells." (PMID 34722315, 2021). "Moreover, their group demonstrated that CDK5RAP3 modulates AKT signaling in both gastric neuroendocrine and cervical carcinoma." (PMID 34722315, 2021).
gastric tumor (2 papers, 2018 to 2019). "Our study demonstrated that CDK5RAP3 expression was markedly decreased in gastric tumor tissues and led to significantly reduced cancer cell proliferation, migration and invasion and tumor xenograft growth by inhibiting β-catenin." (PMID 29540196, 2018). "In patients, immunohistochemistry and immunofluorescence show that the protein levels of CDK5RAP3 were markedly decreased in most gastric tumor tissues compared with adjacent nontumor tissues, and the expression levels of MCM6 in the nucleus showed the opposite trend." (PMID 31528213, 2019). "We analyzed CDK5RAP3, AKT, p-AKT (Ser473), GSK-3β and p-GSK-3β (Ser9) expression in gastric tumor samples and adjacent non-tumor tissues from 295 patients using immunohistochemistry and Western Blotting." (PMID 29540196, 2018). "CDK5RAP3, p-AKT (Ser473) and p-GSK-3β (Ser9) protein levels were detected in gastric tumor tissues and adjacent non-tumor tissues from an additional 86 patients using Western Blotting." (PMID 29540196, 2018). "The protein level of CDK5RAP3 was markedly decreased in most gastric tumor tissues compared with adjacent non-tumor tissues, and the levels of p-AKT (Ser473) and p-GSK-3β (Ser9) were also negatively correlated with those of CDK5RAP3." (PMID 29540196, 2018).
Hypoglycemia (2 papers, 2021). A decreased concentration of glucose in the blood. "Hepatocyte-specific CDK5RAP3 deficient mice also display serious hypoglycemia and lipid metabolism disorders which results in post-weaning lethality." (PMID 34722315, 2021). "Similarly, while CDK5RAP3 deficient mice were not viable, conditional knockdown of CDK5RAP3 incited severe hypoglycemia and substantially impaired the lipid metabolism ultimately causing lethality." (PMID 33578803, 2021).
liver cancer (2 papers, 2022 to 2025). An epithelial or non-epithelial malignant neoplasm that arises from the liver. "Conversely, other studies reported relatively low CDK5RAP3 expression in liver cancer tissues and liver cancer cell lines (HCC), with expression levels significantly associated with prognosis." (PMID 40868283, 2025).
ovarian carcinoma (2 papers, 2015 to 2022). A malignant neoplasm originating from the surface ovarian epithelium. "Finally, we identified common genetic variations in the CDK5RAP3 locus as potentially associated with breast and ovarian cancer risk in BRCA1 and BRCA2 mutation carriers." (PMID 35053516, 2022). "Finally, we identified common genetic variations in the CDK5RAP3 locus as potentially associated with breast and ovarian cancer risk in a large cohort of BRCA1 and BRCA2 mutation carriers." (PMID 35053516, 2022).
Alzheimer disease (1 paper, 2024). A progressive, neurodegenerative disease characterized by loss of function and death of nerve cells in several areas of the brain leading to loss of cognitive function such as memory and language. "Many of these genes have been previously linked to brain-related disorders, including Alzheimer’s disease (WDR12, AGFG2, and CDK5RAP3), schizophrenia (SRA1, WDR55, CORO7, DDAH2, PCDHA8), autism spectrum disorder (MAPK3, PCDHA13), and major depressive disorder (ZMAT2 and ITIH4)." (PMID 39269986, 2024).
breast tumors (1 paper, 2022). "In summary, in addition to the link to cancer risk, our study identifies CDK5RAP3 expression in breast tumors as a new biomarker for poor prognosis and potential target for therapeutic intervention." (PMID 35053516, 2022).
Down syndrome (1 paper, 2023). "Interestingly, UFM1, UFL1, and CDK5RAP3 are all key components of the UFMylation pathway which is an ubiquitin-like posttranslational protein modification, while TTC3 is an E3 ubiquitin ligase highly expressed in the CNS and is closely involved in Down syndrome." (PMID 36917672, 2023).
glioblastoma (1 paper, 2024). The most malignant astrocytic tumor (WHO grade IV). "Mechanistically, TSPAN6 enhanced the malignant progression of glioblastoma by interacting with CDK5RAP3 and regulating STAT3 signaling pathway." (PMID 38725860, 2024). "In this study, we firstly identified the CDK5RAP3 was a TSPAN6-interacting proteins in glioblastoma cells." (PMID 38725860, 2024). "Meanwhile, CDK5RAP3 was overexpressed in glioblastoma compared with normal tissues, and CDK5RAP3 overexpression predicted poor outcomes of glioblastoma patients." (PMID 38725860, 2024). "Because CDK5RAP3 was identified as a potential TSPAN6-interacting protein in glioblastoma cells using LC-MS/MS, and TSPAN6 might be involved in JAK-STAT signaling pathway via gene enrichment analysis of TSPAN6-interacting proteins." (PMID 38725860, 2024). "In addition, TSPAN6 interacted with CDK5 kinase regulatory-subunit associated protein 3 (CDK5RAP3) and regulated STAT3 signaling pathway in glioblastoma." (PMID 38725860, 2024). "Furthermore, TSPAN6 promoted the malignant progression of glioblastoma by interacting with CDK5RAP3 and regulating STAT3." (PMID 38725860, 2024). "Moreover, CDK5RAP3 knockdown could efficiently reverse TSPAN6-induced STAT3 activation in glioblastoma cells." (PMID 38725860, 2024). "Thus, we assumed that TSPAN6 might interact with CDK5RAP3 and enhance the progress of glioblastoma via STAT3." (PMID 38725860, 2024). "Furthermore, TSPAN6 interacted with CDK5RAP3 and promoted the progress of glioblastoma." (PMID 38725860, 2024). "Thus, TSPAN6 may interact with CDK5RAP3 and promote metastatic potential of glioblastoma cells." (PMID 38725860, 2024). "This study demonstrated that TSPAN6 enhanced the phosphorylation of STAT3 in glioblastoma cells, CDK5RAP3 knockdown reversed TSPAN6-activated STAT3, indicating that TSPAN6 activated STAT3 via CDK5RAP3 in glioblastoma cells." (PMID 38725860, 2024). "Furthermore, CDK5RAP3 knockdown successfully reversed the enhanced migrative and invasive abilities induced by TSPAN6 overexpression in glioblastoma cells." (PMID 38725860, 2024). "As we expected, the direct interaction between CDK5RAP3 and STAT3 could also be verified in glioblastoma cells using immunoprecipitation." (PMID 38725860, 2024). "However, the role of CDK5RAP3 in the progress of glioblastoma is not well established." (PMID 38725860, 2024).
inflammatory liver disease (1 paper, 2025). "Therefore, CDK5RAP3 may be a candidate for further investigation in inflammatory liver disease models." (PMID 40868283, 2025).
injury (1 paper, 2026). Damage inflicted on the body as the direct or indirect result of an external force, with or without disruption of structural continuity. "We further investigated the expression profile of CDK5RAP3 in this model and explored its potential involvement in sex-dependent susceptibility to acute liver injury." (PMID 41595493, 2026). "In the present study, both CDK5RAP3 mRNA and protein levels were significantly decreased in CCl4-induced acute liver injury, with a more pronounced decrease observed in male mice." (PMID 41595493, 2026).
male infertility (1 paper, 2026). The inability of the male to effect fertilization of an ovum after a specified period of unprotected intercourse. "Together, these findings identify CDK5RAP3 as an essential regulator of Leydig cell steroidogenesis and provide insight into its potential relevance to male infertility associated with low testosterone." (PMID 41596239, 2026).
neuroblastoma (1 paper, 2025). Neuroblastoma (NB) is the most common solid, extracranial childhood tumor. "CDK5RAP3 is highly expressed in clinical specimens of neuroblastoma (NB) and correlates with poor prognosis in NB patients." (PMID 41179291, 2025).
spermatogenic failure (1 paper, 2026). A male infertility characterized by dirsuption of the process of sperm development from diploid cells into mature haploid spermatozoa. "Using human samples, we found that CDK5RAP3 expression was significantly reduced in Leydig cells from patients with spermatogenic failure (T < 10.4 nmol/L)." (PMID 41596239, 2026). "The fluorescence intensity of CDK5RAP3 in LCs was significantly reduced in spermatogenic failure patients (p < 0.05), and showed a strong positive correlation with HSD3B expression." (PMID 41596239, 2026).
spinocerebellar ataxia (1 paper, 2022). "Meanwhile, several studies have revealed that UFL1 forms a complex with CDK5RAP3 (also known as C53 and LZAP) and UFBP1 proteins, which may be potentially involved in the pathogenesis of spinocerebellar ataxia." (PMID 35884562, 2022).